KLHL34 (kelch like family member 34)
Synonyms: FLJ34960; RP11-450P7.3
Tractability: No criterion of Open Targets' tractability assessment is met for any kind of drug.
Gene: Protein-coding gene on chromosome X (21,654,690 to 21,658,330, reverse strand). Ensembl gene ENSG00000185915.
Gene Ontology:
Biological process: proteasome-mediated ubiquitin-dependent protein catabolic process
Cellular component: extracellular region; Cul3-RING ubiquitin ligase complex
Homologues: Orthologues: chimpanzee KLHL34 (99% identical), macaque KLHL34 (96% identical), pig KLHL34 (90% identical), dog KLHL34 (89% identical), rabbit KLHL34 (88% identical), guinea pig KLHL34 (85% identical), mouse Klhl34 (82% identical), rat Klhl34 (82% identical), tropical clawed frog klhl34 (47% identical). Paralogues in human: KLHL9 (29% identical), KLHL13 (28% identical), KLHL32 (28% identical), KLHL14 (27% identical), KLHL26 (27% identical), KLHL36 (27% identical), KLHL22 (25% identical), KLHL21 (24% identical), KLHL1 (23% identical), KLHL31 (23% identical), KLHL15 (23% identical), KLHL35 (23% identical), and 42 more.
Diseases named in the same sentence as KLHL34 in open-access papers:
KLHL34 is named in the same sentence as 2 diseases in open-access papers, as found by Europe PMC text mining. Sharing a sentence is not in itself a finding about the gene and the disease. The quoted sentences say what the papers report.
rectal cancer (1 paper, 2024). A primary or metastatic malignant neoplasm that affects the rectum. "KLHL34 was found to be hypermethylated in Locally Advanced Rectal Cancer, and knockdown of KLHL34 lowered colony formation, increased cytotoxicity, and increased radiation induced caspase 3 activity in LoVo cells." (PMID 39484215, 2024).
cancer (2 papers, 2015 to 2019). A tumor composed of atypical neoplastic, often pleomorphic cells that invade other tissues. "The function of Klhl34 is not completely understood, but its underexpression has been associated with resistance to radiation and chemotherapy in cancer." (PMID 30934014, 2019). "Most of these genes have not been previously reported in SS, and neuroguidin (NGDN), RAS protein activator like 3 (RASAL3), KLHL34 and MUM1L1 have not previously been linked to cancer; only one gene (EP300) has been reported in SS." (PMID 26503545, 2015). "Most of these genes have not been previously reported in SSs, and four genes, neuroguidin (NGDN), RAS protein activator like 3 (RASAL3), KLHL34 and MUM1L1, have not been previously linked to cancer." (PMID 26503545, 2015).